HIKESHI (heat shock protein nuclear import factor hikeshi)
Description:
Acts as a specific nuclear import carrier for HSP70 proteins following heat-shock stress: acts by mediating the nucleoporin-dependent translocation of ATP-bound HSP70 proteins into the nucleus. HSP70 proteins import is required to protect cells from heat shock damages. Does not translocate ADP-bound HSP70 proteins into the nucleus.
Synonyms: C11orf73; HSPC138; HSPC179; OPI10; HLD13; L7RN6
Tractability: PROTAC: ubiquitination databases record sites on it.
Gene: Protein-coding gene on chromosome 11 (86,302,181 to 86,345,943, forward strand). Ensembl gene ENSG00000149196.
Subcellular location: Cytoplasm; Cytoplasm, cytosol; Nucleus
Subcellular location (Human Protein Atlas): Nuclear speckles; Nuclear bodies; Nucleoplasm
Pathways (Reactome):
Cellular responses to stimuli: Regulation of HSF1-mediated heat shock response
Gene Ontology:
Molecular function: Hsp70 protein binding; nuclear import signal receptor activity; protein binding
Biological process: cellular response to heat; protein import into nucleus; protein transport
Cellular component: cytosol; nucleus; cytoplasm; nucleoplasm
Genetic constraint (gnomAD): Loss-of-function variants: 6 observed, 12.87 expected, observed/expected ratio (o/e) 0.47, 90% interval 0.25 to 0.92. The upper end of that interval is the gene's LOEUF score, 0.92, which puts it in group 3 of 6, group 1 being the genes least tolerant of losing a copy. Missense variants: 121 observed, 156.35 expected, observed/expected ratio (o/e) 0.77, 90% interval 0.67 to 0.9. Synonymous variants: 49 observed, 52.34 expected, observed/expected ratio (o/e) 0.94, 90% interval 0.74 to 1.19.
Gene-disease validity (ClinGen):
ClinGen rates the evidence that HIKESHI causes each of these diseases.
hypomyelinating leukodystrophy 13 (autosomal recessive): Definitive. Any leukodystrophy in which the cause of the disease is a mutation in the HIKESHI gene.
Homologues: Orthologues: chimpanzee HIKESHI (100% identical), macaque HIKESHI (100% identical), dog HIKESHI (98% identical), pig HIKESHI (98% identical), rabbit HIKESHI (97% identical), mouse Hikeshi (97% identical), rat Hikeshi (97% identical), guinea pig HIKESHI (96% identical), tropical clawed frog hikeshi (88% identical), zebrafish hikeshi (72% identical), Drosophila melanogaster CG13926 (47% identical), Caenorhabditis elegans F42A6.6 (35% identical).
Diseases named in the same sentence as HIKESHI in open-access papers:
HIKESHI is named in the same sentence as 14 diseases in open-access papers, as found by Europe PMC text mining. Sharing a sentence is not in itself a finding about the gene and the disease. The quoted sentences say what the papers report.
clear cell renal cell cancer (1 paper, 2023). "HIKESHI c11orf73 was also reported as one of the gene-based biomarkers that overexpresses in the late stage of clear cell renal cell cancer." (PMID 36839948, 2023).
gastric cancer (1 paper, 2023). A primary or metastatic malignant neoplasm involving the stomach. "HIKESHI expression, first demonstrated in HeLa cells under heat shock, is key to heat tolerance in a gastric cancer cell line and human tongue squamous carcinoma cell line." (PMID 36839948, 2023).
heart failure (1 paper, 2020). Inability of the heart to pump blood at an adequate rate to meet tissue metabolic requirements. "Heat shock proteins are involved in protecting the heart against heart failure by facilitating the removal of misfolded and degraded proteins, and HIKESHI plays a role in heat-shock stress response regulation to protect cells from heat shock damages." (PMID 33240937, 2020).
thymoma (1 paper, 2018). A neoplasm arising from the epithelial cells of the thymus. "A third translocation involving C11orf73 (current gene name is HIKESHI) and TENM1 was detected in an advanced B3 thymoma." (PMID 30618566, 2018).
HIKESHI also shares sentences with these, for which no sentence is quoted: cancer (2 papers); Leukoencephalopathy (2); acute coronary syndrome (1); Bardet-Biedl syndrome (1); developmental delay (1); hypomyelinating leukoencephalopathy (1); Joubert syndrome (1); primary ciliary dyskinesia (1); Walker Warburg syndrome (1); Zellweger syndrome (1).